IL10 (interleukin 10)
Diseases named in the same sentence as IL10 in open-access papers (continued):
Sharing a sentence is not in itself a finding about the gene and the disease.
mesothelioma (7 papers, 2018 to 2023). A usually malignant and aggressive neoplasm of the mesothelium which is often associated with exposure to asbestos. "Murine mesothelioma induces locally-proliferating IL-10+TNF-αCD206−CX3CR1+ M3 macrophages that can be selectively depleted by chemotherapy or immunotherapy." (PMID 31998326, 2019). "Other key cytokines for macrophage activation such as TGF-β and IL-10 have been identified in pleural fluid and supernatant from mesothelioma cultures, also suggesting a tumor origin." (PMID 31867277, 2019). "Furthermore, for the specific activation of macrophages, transforming growth factor beta (TGF-β) and IL-10 have also been identified, in addition to the pleural effusions, also in the supernatant from mesothelioma cultures and in mesothelioma tissue samples via immunohistochemistry." (PMID 38259475, 2023). "Our published findings in NSCLC, mesothelioma and ovarian MPE reveal a profound degree of polarization dominated by near nM concentrations of IL-6/sIL6Rα, IL-8, IL10, VEGF, FGF2 and CXCL10." (PMID 37063842, 2023).
mood disorder (7 papers, 2013 to 2025). A cognitive disorder a disturbance in which the person's mood is hypothesized to be the main underlying feature. "Although IL-10 plays a role in RA and has previously been linked with mood disorders, there has been insufficient evidence for a specific role for IL-10 in regulating behavior during inflammatory arthritis." (PMID 37220589, 2016). "Significantly increased levels of TGF-β, IL-10, and IL-6 in SD compared to MD or ND subjects can suggest the role of cytokines in mood disorders in SD group." (PMID 38646609, 2024). "Tregs are involved in the immunopathology of T. gondii through surface factors (CTLA-4) and cytokines (TGF-β and IL-10), and similarly, Tregs may regulate T. gondii-induced mood disorders through this immune mechanism." (PMID 37077528, 2023). "Findings from previous research showed that an imbalance between pro- and anti-inflammatory cytokines demonstrated through a higher ratio of TNF-α/IL-10 and IL-6/IL-10 in the brain of animals exposed to chronic mild stress, may contribute to mood disorders." (PMID 33810574, 2021). "The observation that Il10-/- mice have prolonged behavioral and anxiety-related impairments post-AIA may be important for addressing the high prevalence of mood disorders in patients with RA." (PMID 37220589, 2016). "However, T. gondii infection often leads to a decrease in Tregs levels, which may exacerbate the symptoms of T. gondii -induced mood disorders, suggesting that Tregs and the cytokines TGF-β and IL-10 are important modulators." (PMID 37077528, 2023).
Oral ulcer (7 papers, 2019 to 2026). Erosion of the mucous mebrane of the mouth with local excavation of the surface, resulting from the sloughing of inflammatory necrotic tissue. "rs1800871, a variant within 1 kb 5′ of IL10, showed the second strongest evidence for association after meta-analysis, conferring a large effect on mouth ulcers (OR 1.18 per A allele, 95% CI: 1.17, 1.19; EAF 0.22; P = 6.0e−236)." (PMID 30837455, 2019). "Mouth ulcers were found to be highly correlated to SNPs in IL-12A in addition to significant relation to other genes including IL-10." (PMID 34539639, 2021). "Other single variant results were mirrored in the results of this analysis with increased expression of SCHIP1 increasing the odds of mouth ulcers and IL10 decreasing the odds of mouth ulcers (P = 8.99e−70 and 5.60e−55, respectively)." (PMID 30837455, 2019). "Moreover, infantile-IBD patients with complex perianal disease, intractable early onset enterocolitis and extraintestinal manifestations including oral ulcers and skin folliculitis, should undergo genetic and functional testing for IL-10 pathway defect." (PMID 34032699, 2021).
Peptic ulcer (7 papers, 2013 to 2025). The term peptic ulcer refers to acid peptic injury of the digestive tract, resulting in mucosal break reaching the submucosa. "Furthermore, individuals with blood group O was found to had higher risk to peptic ulceration due to an increasing density of colonization of epithelial cells and higher inflammatory responses (release of IL-6, IL-10 and TNF-α) to H. pylori.." (PMID 29088730, 2017). "Inflammation is a pivotal pathological reaction of ethanol-related peptic ulcer, which is mainly characterized by increased secretion of diverse proinflammatory factors, such as TNF-α, IL-6, and IL-1β, and inhibition of the production of anti-inflammatory cytokines such as IL-10." (PMID 32325708, 2020).
pneumococcal meningitis (7 papers, 2012 to 2026). An acute purulent infection of the meninges and subarachnoid space caused by Streptococcus pneumoniae, most prevalent in children and adults over the age of 60. "We also measured CSF IL-1β, TNF-α, IL-10 and IL-17A concentrations in 402 patients with pneumococcal meningitis (Appendix p9)." (PMID 41161094, 2025). "The anti-inflammatory cytokines known to be involved in pneumococcal meningitis are IL-10 and TGFβ." (PMID 39121090, 2024). "Indeed, levels of IL-10, an important anti-inflammatory mediator with a protective function in pneumococcal meningitis, are significantly decreased in C/EBPδ−/− mice as compared to wild-type mice." (PMID 25958220, 2015). "The anti-inflammatory cytokine IL-10 has been implicated in playing a role in modulating the immune response by downregulating TNF, IL-6, and keratinocyte-derived chemokine (KC), thereby reducing CSF pleocytosis in pneumococcal meningitis." (PMID 23997430, 2013). "Also, intravenously administered recombinant IL-10 reduced the levels of CSF pleocytosis, cerebral edema, and intracranial pressure in a rat model of pneumococcal meningitis." (PMID 23997430, 2013). "In our study, we confirm the established role of C/EBPδ as activator of the inflammatory response, reflected by the reduction in IL-10 and KC levels in the brain and IL-6, IL-10, KC, and MIP-2 in plasma during pneumococcal meningitis." (PMID 25958220, 2015). "IL-8 appears to regulate CSF pleocytosis in pneumococcal meningitis from the systemic compartment, similar to that seen for TNF, IL-10, and TGF-β." (PMID 23997430, 2013). "IL-1β, IL-2, IL-4, IL-10, IL-12p70, IL-17, RANTES, TNF-α, IL-18 and IL-33 were not significantly altered in the plasma of mice with pneumococcal meningitis compared to sham controls." (PMID 22455545, 2012). "IL-2, IL-4, IL-10, IL-12p70, IL-17, IFN-γ, TNF-α, IL-18 and IL-33 were not altered in brain homogenates of mice with pneumococcal meningitis compared to sham controls." (PMID 22455545, 2012).
polyposis (7 papers, 2014 to 2025). "The intricate biological relationship between IL-10 and polyposis necessitates further experimentation to elucidate the mechanisms underlying their interaction." (PMID 39814702, 2025). "In another study, it was demonstrated that the adoptive transfer of T cells secreting IL-10 attenuated microbial-induced inflammation, suppressing polyposis in APC∆458 mice." (PMID 32674255, 2020). "In small polyposis MMCs expanded in an IL10 dependent manner and both IL10 and MMCs were essential for polyp growth." (PMID 31849960, 2019). "Many studies have investigated molecular factors such as interleukin 5, interleukin 10, TGF-B, etc., in polyposis." (PMID 38259689, 2024). "In the mouse model of polyposis with hereditary deletion of the APCA gene, the levels of IL-10, IL-13, and IL-33 were elevated, and the population of type 2 innate lymphoid cells (ILC2s) was enriched, Meanwhile, mast cells exhibited a localized expansion in this context." (PMID 39814702, 2025). "Using mice singly infected with H. typhlonius or H. mastomyrinus, we showed that VitC treatment also reduced polyposis and levels of 8-oxoG in IL10−/− mice without major effects on inflammation or Helicobacter colonization." (PMID 32286276, 2020). "Interestingly, despite a massive expansion of mast cell in polyposis-prone mice, overexpression of IL-10 by T cells does not lead to an increase in polyp formation." (PMID 39814702, 2025).
renal carcinoma (7 papers, 2006 to 2025). A carcinoma arising from the epithelium of the renal parenchyma or the renal pelvis. "It has been reported that BMP6 promotes tumor proliferation through IL-10-dependent M2 polarization of tumor-associated macrophages in renal carcinoma." (PMID 26029998, 2015). "The aim of the present study was to examine C-reactive protein, interleukin-6 and interleukin-10 concentrations before and following curative resection of renal cancer." (PMID 17003778, 2006). "Furthermore, a study of renal cancer found significant positive correlations between tumor TL and peripheral levels of IL-8 and IL-10." (PMID 24475279, 2014). "Renal cancer cells (RCCs) exhibited overexpression of 15-LOX that resulted in the production of hydroperoxy products, i.e., cytokine interleukin-10 (IL-10) and pro-inflammatory chemokine CCL2." (PMID 36557863, 2022).
Rotavirus infection (7 papers, 2018 to 2024). Infection with any of the rotaviruses. "The RV infection produced significant increases in both pro-inflammatory/Th1 (IL-12, IL-6) and anti-inflammatory/Th2 (IL-10) cytokines at the peak of infection, as found in several rotavirus infection models." (PMID 30406046, 2018). "Our results indicated that, in HT-29 cells with both microorganisms before rotavirus infection, the relative expression of SOCS3, IFN-γ, STAT1, and IL-10 was significantly (p < 0.05) upregulated." (PMID 38791551, 2024). "Previous reports demonstrated that rotavirus infection led to increased levels of Lachnospiraceae and increased mRNA expression of IFN-γ, IL-8, and IL-10 in the ileum of pigs." (PMID 30713531, 2018). "The mechanism by which aspirin reduces rotavirus infection may involve the inhibition of rotavirus-induced expression of COX-2, IL-2 and/or IL-10." (PMID 37848986, 2023).
septic peritonitis (7 papers, 2015 to 2024). Septic peritonitis is an inflammatory condition of the peritoneum that occurs secondary to microbial contamination. "Moreover, it was shown that IL-10 is a key factor in terms of protecting mice from death caused by septic peritonitis." (PMID 35203386, 2022). "Some report that IL-10 actually impairs host defense against S. pneumoniae, whereas others report that IL-10 is protective in models of septic peritonitis." (PMID 25595646, 2015). "IL-10 promotes survival in mice with septic peritonitis, suggesting an anti-inflammatory effect." (PMID 38696304, 2024). "Mice challenged with septic peritonitis had significantly higher plasma levels of TNF-α, IL-6, IL-10, and IFN-γ compared to the sham-operated mice." (PMID 34366711, 2021). "To get insight into the influence of gzmA and gzmB deficiency on the local inflammatory response elicited during septic peritonitis, we measured proinflammatory (TNF-α, IFN-γ, and IL-1β, IL-6) and anti-inflammatory (IL-10) cytokines as well as MCP-1 and KC levels in PLF." (PMID 28694562, 2017).
spinal cord injury (7 papers, 2019 to 2024). Penetrating and non-penetrating injuries to the spinal cord resulting from traumatic external forces (e.g., WOUNDS, GUNSHOT; WHIPLASH INJURIES; etc.). "Targeted delivery of IL-10 in animal models of spinal cord injury (SCI) has demonstrated significant achievements, indicating the potential application of IL-10 in clinical settings for SCI patients." (PMID 37492521, 2023). "The anti-inflammatory cytokine interleukin-10 (IL-10) has been explored previously as a treatment method for spinal cord injury (SCI) due to its ability to attenuate pro-inflammatory cytokines and reduce apoptosis." (PMID 31039819, 2019). "The ongoing research exploring various strategies for harnessing the potential of IL-10 offers hope for the development of effective treatments that could significantly improve outcomes for individuals suffering from spinal cord injuries." (PMID 38248028, 2024). "The levels of cytokines CXCL5, CCL11, CXCL11, IL10, TNFα, and MIF were different between patients with baseline American Spinal Injury Association Impairment Scale (AIS) grades of A or B, whilst IL2 (>2 fold) and MIP-3a (>6 fold) were significantly expressed in the cervical and thoracic regions." (PMID 33806460, 2021). "For instance, it has been found that electroacupuncture reduced the proportion of M1 macrophages and the levels of TNF-α, IL-1 β, and IL-6 in rats with spinal cord injury and also increased the amount of IL-10 and M2 macrophages and upregulated the expression of the M2 markers CD206 and NT-3." (PMID 33727948, 2021).
sporotrichosis (7 papers, 2016 to 2025). The commonest and least serious of the deep mycoses, characterized by nodular lesions of the cutaneous and subcutaneous tissues. "In peritoneal macrophages of mice with sporotrichosis, a correlation has been shown between the presence of TLR-4 and the secretion of both pro-inflammatory (TNF-α) and anti-inflammatory (IL-10) mediators during sporotrichosis." (PMID 34358055, 2021). "IL-10 was significantly increased in cats with sporotrichosis co-infected with either FIV or FeLV, leading to a potential immunosuppressive condition, since this cytokine is widely involved with immunoregulatory effects." (PMID 30500849, 2018). "In experimental murine sporotrichosis, IL-10 is involved with impairment of fungicidal activity of macrophage, as well as with unresponsiveness of T-cells." (PMID 30500849, 2018). "Further in vivo studies are necessary to establish the role of IL-10 in sporotrichosis." (PMID 35628694, 2022). "In situ IL-10 expression in lymphocutaneous (LC) and fixed (F) forms of sporotrichosis." (PMID 27622513, 2016). "In the most severe cases of feline sporotrichosis, co-infection with FIV or FLV has been reported, which is known to cause feline immunosuppression with low CD4+/CD8+ ratio and decreased levels of IL-4 and IL-12 and high levels of the anti-inflammatory interleukin IL-10." (PMID 37233242, 2023). "In an ex vivo sporotrichosis model using peritoneal exudate cells challenged with S. schenckii cell wall peptide-polysaccharide complex, M2 macrophages were the most predominant population, and expressed arginase-I activity peaks as well as IL-10 and transforming growth factor-beta." (PMID 37746241, 2022). "Based on these facts and aiming at understanding some aspects of the IFN-γ/IL-10 profile in the different clinical presentations and tissue compartment of human sporotrichosis, we quantified the systemic and in situ IFN-γ and IL-10 expressions by immunohistochemistry and Elispot assay." (PMID 27622513, 2016). "Cats coinfected with these viruses show some differences in cytokine levels, showing higher levels of IL-10 and lower levels of IL-4, IL-12, and CD4+/CD8+, compared to other cats with sporotrichosis without coinfection with these viruses." (PMID 37233242, 2023).
staphylococcus aureus infection (7 papers, 2011 to 2025). An infectious process in which the bacteria Staphylococcus aureus is present. "In the past, Th2 type cytokines IL-4 and IL-10 were associated with resistance to Staphylococcus infection in mice." (PMID 21857913, 2011). "The KEGG pathways associated with AD were mainly involved in the IL-10 signaling pathway, IL-4 and IL-13 signaling, TGF-beta receptor signaling, the TCR pathway during Staphylococcus aureus infection signaling, and the STAT3 pathways." (PMID 41471858, 2025). "In a piglet model of Staphylococcus aureus infection, post-infection, B. infantis supplementation increased serum IL-10 level concentrations and decreased memory T-cell populations." (PMID 39525504, 2024). "In a piglet model of Staphylococcus aureus infection, piglets supplemented with B. infantis (ATCC 15697) at 3 × 109 CFU/day had increased serum IL-10, potentially as an attempt by the immune system to reduce the inflammatory response." (PMID 39525504, 2024). "In models of Staphylococcus aureus infection, LF increases pro-inflammatory cytokine TNF-α levels while decreasing interleukin-5 (IL-5) and interleukin-10 (IL-10) levels, confirming that LF accelerates the inflammatory response of host organisms to the infection." (PMID 40003872, 2025). "A previous study, using a Staphylococcus aureus infection model, identified two distinct neutrophil subsets, described as PMN-I and PMN-II with their dichotomous gene expression patterns characterized by highly expressed IL-12 and IL-10, respectively." (PMID 33995406, 2021).
trypanosomiasis (7 papers, 2011 to 2024). Infection with protozoa of the genus trypanosoma. "At the onset of trypanosomiasis, IL-10 downregulates IFN-γ and TNF-α secretion relieving inflammatory feedback." (PMID 38620045, 2024). "However, exceptions have been noted as during infection by T. gondii or M. bovis where TLR-mediated signaling is required or during development of trypanosomiasis where IL-10-mediated mechanisms were invoked." (PMID 21246055, 2011). "Moreover, interleukin-4 (IL-4), IL-10 and Transforming Growth Factor-β (TGF-β), which are potent arginase inducers, are enhanced in experimental trypanosomiasis." (PMID 21408057, 2011).
Airway obstruction (6 papers, 2008 to 2023). Obstruction of conducting airways of the lung. "For instance, tumor necrosis factor-alpha (TNF-α) and interleukin-10 (IL-10) represent pro- and anti-inflammatory cytokines, respectively, and polymorphisms in TNF-α and IL-10 have been associated with obstructive lung disease, a complex disease characterized by airway obstruction and inflammation." (PMID 20459696, 2010). "Intratracheal BMNC delivery in horses affected with recurrent airway obstruction resulted in 30-fold higher IL-10 concentrations in bronchoalveolar lavage fluid compared to horses treated with dexamethasone." (PMID 37876630, 2023). "Decreased percentages of IL-10 + B-regs were observed in peripheral blood of smokers without airway obstruction and COPD patients, compared to healthy controls." (PMID 36253785, 2022). "Within total B cells and B cell subsets, percentages of cells producing IL-10 were attenuated in smokers without airway obstruction and patients with COPD, compared to healthy controls." (PMID 36253785, 2022).
alcohol abuse (6 papers, 2013 to 2022). The use of alcoholic beverages to excess, either on individual occasions ("binge drinking") or as a regular practice. "Alcohol abuse increases IL-4 and IL-10 levels as well as TGF-beta expression in the liver, thus inducing alternatively activated M2 macrophages." (PMID 28566719, 2017).
alcoholic cirrhosis (6 papers, 2013 to 2024). "Single-nucleotide polymorphisms in IL-1β (−511C/T), IL-10 (−592C/A), TNF-α (−308G/A, −238G/A), TGF-β1 (−509C/T) and CTLA4 (+49A/G) were assessed in a South Indian population of 181 patients with alcoholic cirrhosis and 110 controls." (PMID 26343741, 2015). "IL-12, IL-6 and TNF-α levels were higher in alcoholic cirrhosis (p < 0.05 for all), while IL-1β and IL-10 levels were comparable between patients with alcoholic or HCV cirrhosis." (PMID 26343741, 2015). "Cells of monocyte-macrophage lineage secrete IL-10 in response to endotoxin and their secretion capacity is not impaired but even pronounced in alcoholic cirrhosis." (PMID 23446058, 2013). "Besides elevated IL-10 concentrations, low serum levels of IFN-γ might have contributed to the impaired monocyte HLA-DR expression as observed in patients with alcoholic cirrhosis." (PMID 23446058, 2013).